IGKV1D-8 (immunoglobulin kappa variable 1D-8)
Description:
V region of the variable domain of immunoglobulin light chains that participates in the antigen recognition. Immunoglobulins, also known as antibodies, are membrane-bound or secreted glycoproteins produced by B lymphocytes. In the recognition phase of humoral immunity, the membrane-bound immunoglobulins serve as receptors which, upon binding of a specific antigen, trigger the clonal expansion and differentiation of B lymphocytes into immunoglobulins-secreting plasma cells. Secreted immunoglobulins mediate the effector phase of humoral immunity, which results in the elimination of bound antigens. The antigen binding site is formed by the variable domain of one heavy chain, together with that of its associated light chain. Thus, each immunoglobulin has two antigen binding sites with remarkable affinity for a particular antigen. The variable domains are assembled by a process called V-(D)-J rearrangement and can then be subjected to somatic hypermutations which, after exposure to antigen and selection, allow affinity maturation for a particular antigen.
Synonyms: IGKV1D8; L24; L24a
Gene: Immunoglobulin variable (V) gene on chromosome 2 (90,220,727 to 90,221,384, forward strand). Ensembl gene ENSG00000239819.
Subcellular location: Secreted; Cell membrane
Gene Ontology:
Biological process: immune response
Cellular component: extracellular region; immunoglobulin complex; plasma membrane
Homologues: Orthologues: mouse Igkv15-103 (68% identical). Paralogues in human: IGKV1-8 (92% identical), IGKV1-9 (88% identical), IGKV1-39 (87% identical), IGKV1D-39 (87% identical), IGKV1-12 (86% identical), IGKV1D-13 (86% identical), IGKV1-27 (85% identical), IGKV1-6 (85% identical), IGKV1D-12 (85% identical), IGKV1D-16 (85% identical), IGKV1D-43 (85% identical), IGKV1-16 (84% identical), and 81 more.
Diseases named in the same sentence as IGKV1D-8 in open-access papers:
IGKV1D-8 is named in the same sentence as 1 disease in open-access papers, as found by Europe PMC text mining. Sharing a sentence is not in itself a finding about the gene and the disease.
IGKV1D-8 shares sentences with these, for which no sentence is quoted: tumor (1 paper).